RUBCNL (rubicon like autophagy enhancer)
Description:
Regulator of autophagy that promotes autophagosome maturation by facilitating the biogenesis of phosphatidylinositol 3-phosphate (PtdIns(3)P) in late steps of autophagy. Acts by antagonizing RUBCN, thereby stimulating phosphatidylinositol 3-kinase activity of the PI3K/PI3KC3 complex. Following anchorage to the autophagosomal SNARE STX17, promotes the recruitment of PI3K/PI3KC3 and HOPS complexes to the autophagosome to regulate the fusion specificity of autophagosomes with late endosomes/lysosomes. Binds phosphoinositides phosphatidylinositol 3-phosphate (PtdIns(3)P), 4-phosphate (PtdIns(4)P) and 5-phosphate (PtdIns(5)P). In addition to its role in autophagy, acts as a regulator of lipid and glycogen homeostasis (By similarity). May act as a tumor suppressor (Probable).
Synonyms: Pacer; C13orf18; KIAA0226L; FLJ21562
Tractability: Antibody: UniProt places it where antibodies can reach, with high confidence. PROTAC: ubiquitination databases record sites on it.
Gene: Protein-coding gene on chromosome 13 (46,334,681 to 46,438,190, reverse strand). Ensembl gene ENSG00000102445.
Subcellular location: Cytoplasmic vesicle, autophagosome membrane
Subcellular location (Human Protein Atlas): Cytosol
Gene Ontology:
Molecular function: phosphatidylinositol-3-phosphate binding; phosphatidylinositol-4-phosphate binding; phosphatidylinositol-5-phosphate binding; protein binding; phosphatidylinositol phosphate binding
Biological process: autophagosome maturation; autophagosome-endosome fusion; autophagosome-lysosome fusion; regulation of lipid metabolic process
Cellular component: autophagosome membrane
Genetic constraint (gnomAD): Loss-of-function variants: 49 observed, 51.14 expected, observed/expected ratio (o/e) 0.96, 90% interval 0.76 to 1.22. The upper end of that interval is the gene's LOEUF score, 1.22, which puts it in group 5 of 6, group 1 being the genes least tolerant of losing a copy. Missense variants: 670 observed, 688.77 expected, observed/expected ratio (o/e) 0.97, 90% interval 0.91 to 1.04. Synonymous variants: 251 observed, 266.25 expected, observed/expected ratio (o/e) 0.94, 90% interval 0.85 to 1.05.
Homologues: Orthologues: chimpanzee RUBCNL (99% identical), macaque RUBCNL (88% identical), pig RUBCNL (71% identical), rabbit RUBCNL (71% identical), guinea pig RUBCNL (70% identical), mouse Rubcnl (61% identical), dog RUBCNL (61% identical), rat Rubcnl (60% identical), tropical clawed frog rubcnl (37% identical), zebrafish rubcnl (23% identical), Caenorhabditis elegans cup-14 (16% identical), Drosophila melanogaster Plekhm1 (15% identical). Paralogues in human: RUBCN (35% identical), PLEKHM1 (21% identical), PLEKHM3 (18% identical), DEF8 (15% identical).
Diseases named in the same sentence as RUBCNL in open-access papers:
RUBCNL is named in the same sentence as 14 diseases in open-access papers, as found by Europe PMC text mining. Sharing a sentence is not in itself a finding about the gene and the disease. The quoted sentences say what the papers report.
cervical cancer (6 papers, 2015 to 2025). A primary or metastatic malignant neoplasm involving the cervix. "Promoter methylation of RUBCNL was identified as a potential biomarker for early diagnosis of cervical cancer." (PMID 33098370, 2020).
colorectal cancer (6 papers, 2024 to 2025). A primary or metastatic malignant neoplasm that affects the colon or rectum. "In colorectal cancer, histone lactation enhances the expression of the oncogene RUBCNL and promotes resistance to bevacizumab, a specific targeted therapy for anti-angiogenic genesis, in CRC." (PMID 40843350, 2025). "Existing research indicates aerobic glycolysis-induced high histone lactylation levels enhance Rubicon Like Autophagy Enhancer (RUBCNL) transcription, which stimulates autophagy by promoting autophagosome maturation to further aggravate colorectal cancer." (PMID 40057816, 2025). "Higher levels of H3K18la subsequently increase RUBCNL transcription, thereby contributing to colorectal cancer cell survival and treatment resistance." (PMID 39417674, 2024). "In colorectal cancer, H3K18la promotes transcription of CXCL1, CXCL5, and RUBCNL, enhancing resistance to bevacizumab and 5-FU." (PMID 40843350, 2025).
colon cancer (1 paper, 2019). "Tumour-suppressor genes (MLH1 and RUBCNL), protooncogene (AGR2), and genes reported to be linked with colon cancer (EPDR1, MLH1, AXIN2) were enriched in the signature." (PMID 31008109, 2019).
leukemia (1 paper, 2021). A malignant (clonal) hematologic disorder, involving hematopoietic stem cells and characterized by the presence of primitive or atypical myeloid or lymphoid cells in the bone marrow and the blood. "RUBCNL is a gene for which no prior knowledge exists for its role in leukemia." (PMID 34072627, 2021).
tumor (6 papers, 2019 to 2025). "In CRC, tumor-derived lactate promotes H3K18la, thereby enhancing the expression of autophagy-enhancing protein RUBCNL, which contributes to resistance against bevacizumab treatment." (PMID 39010066, 2024). "Lactylation modifications are significantly upregulated in these resistant tumour cells, increasing the expression of RUBCNL and promoting autophagosome maturation, ultimately enhancing tumour survival and proliferation." (PMID 39456119, 2024). "Furthermore, tumor-derived lactate promotes autophagy through H3K18lac-enhanced RUBCNL expression, thereby promoting resistance." (PMID 39010066, 2024).
infection (2 papers, 2019 to 2025). The state of being infected such as from the introduction of a foreign agent such as serum, vaccine, antigenic substance or organism. "Other genes encoding nascent autophagosome inhibitors or regulators of macroendosome biogenesis were upregulated in MAP-infected JD(–) macrophages, notably RUBCNL from 1 hpi and throughout the infection period." (PMID 31969876, 2019). "HTi pDCs also showed elevated RUBCNL (autophagy),59BCL11A (enhances Bcl-2 and pDC development), and PRXL2A (redox regulation), reinforcing the notion of autophagy activation and mitochondrial stress in response to infection." (PMID 41321641, 2025).
RUBCNL also shares sentences with these, for which no sentence is quoted: cancer (5 papers); cervical dysplasia (2); breast carcinoma (1); cervical tumor (1); invasive carcinoma (1); metastatic colorectal cancer (1); ovarian carcinoma (1); pancreatic cancers (1).